HDAC3 (histone deacetylase 3)
Diseases named in the same sentence as HDAC3 in open-access papers (continued):
Sharing a sentence is not in itself a finding about the gene and the disease.
melanoma (30 papers, 2014 to 2025). A malignant, usually aggressive tumor composed of atypical, neoplastic melanocytes. "The treatment of melanoma cells and B16F10 melanomas by rhARSB leads to increased HDAC3, reduced acetyl-H3 antibody association with the PD-L1 promoter, and reduced PD-L1 expression." (PMID 38892038, 2024). "Based on these findings, we propose that constitutively expressed IκBζ in melanoma recruits HDAC3 and EZH2 to the gene loci of CXCL9, CXCL10, and CCL5, leading to inaccessible promoter regions of these genes." (PMID 40562773, 2025). "In the subcutaneous mouse melanoma tissue, HDAC3 activity increased following exogenous ARSB (p < 0.0001), in contrast to the decline in free galectin-3." (PMID 38892038, 2024). "HDAC3 has also been found to be involved in the development of many other malignancies, such as melanoma, gastric cancer, ovarian cancer, and children glioma." (PMID 37553641, 2023). "The elevated expression of HDAC3 has been attributed to the downregulation of a series of tumor suppressor micro-RNAs including miR-296-3p, miR-451, and miR-495-3p in colorectal, melanoma, and prostate cancer, respectively." (PMID 35110603, 2022). "HDAC3 is an epigenetic regulator of a variety of cell signaling pathways, also the knockdown of HDAC3 promotes the G0/G1 cell cycle arrest which subsequently induces cell apoptosis in acute myeloid leukemia, prostate, melanoma, and colorectal cancer." (PMID 35110603, 2022). "miR-326 acted as a negative regulator of HDAC3 and enhanced the invasion and migration of melanoma cells." (PMID 35682560, 2022). "HDAC3 enhanced the sensitivity of anti-cancer drug-resistant melanoma cells to anti-cancer drugs by negatively regulating EGFR signaling and CAGE expression." (PMID 35682560, 2022). "The downregulation of tubulin β3 by HDAC3 enhanced the sensitivity of melanoma cells to microtubule-targeting agents." (PMID 35682560, 2022). "Relation between HDAC3/miR‐495‐3p expression and pathological features of melanoma patients was analysed." (PMID 33048450, 2020). "We conducted the Kaplan‐Meier survival analysis to evaluate the predictive role of HDAC3/miR‐495‐3p expression in prognosis of patients with melanoma." (PMID 33048450, 2020). "The melanoma cells were screened and transfected with relative oligonucleotides and plasmids, and the expression of HDAC3, miR‐495‐3p and TRAF5, and phenotypes of melanoma cells were gauged by a series of assays." (PMID 33048450, 2020). "In summary, we demonstrated that reduced HDAC3 was able to up‐regulate miR‐495‐3p to suppress malignant behaviours of melanoma cells, thereby decelerating the development of melanoma with the involvement of TRAF5." (PMID 33048450, 2020). "We further discussed the role of HDAC3/miR‐495‐3p/TRAF5 in the biological functions of melanoma cells in vivo and in vitro using MTT assay, colony formation assay and subcutaneous tumorigenesis in nude mice." (PMID 33048450, 2020). "This study was designed to investigate effect of the HDAC3/miR‐495‐3p/TRAF5 axis in the development of melanoma, and we found that the inhibition of HDAC5 has the ability to elevate miR‐495‐3p to restrain the progression of melanoma by reducing TRAF5." (PMID 33048450, 2020). "For example, Xia et al13 have suggested that miR‐495‐3p was markedly decreased in melanoma cells, and a former study has revealed that HDAC3 was highly expressed in melanoma samples, especially in tumour‐invaded regions, in relation to non‐melanoma samples." (PMID 33048450, 2020). "Melanoma cells that are naturally resistant to anti-cancer drugs also showed lower expression of HDAC3 than anti-cancer drug-sensitive melanoma cells." (PMID 30583572, 2018). "MiR-335 binds to 3′-UTR of SIAH2 and decreases expression of SIAH2, which in turn increases the expression of HDAC3 to confer anti-cancer drug sensitivity in anti-cancer drug-sensitive melanoma cells, such as Malme3M cells." (PMID 30583572, 2018).
melanoma (continued). "Among various HDACs, HDAC3 can inhibit the invasion, migration, and angiogenic potential of hepatic cancer cell lines and melanoma cell lines." (PMID 30583572, 2018). "In melanoma cells knock down of [HDAC6 + HDAC2] or [HDAC6 + HDAC10] significantly enhanced pazopanib lethality whereas knock down of [HDAC6 + HDAC1] or [HDAC6 + HDAC3] were less effective." (PMID 29137331, 2017). "Our results suggest that down-regulation of HDAC3 is a potential therapeutic strategy to inhibit the melanoma cell proliferation." (PMID 25521755, 2014). "The potent HDAC3 inhibitor (MS-275) was also tested with regards to melanoma cell proliferation, and also showed an antiproliferative effect." (PMID 25521755, 2014). "We used an immunohistochemical approach to analyze HDAC3 expression in melanoma patients' specimens compared to that of normal tissues." (PMID 25521755, 2014). "In this study, we showed that Rg3 in combination with HDAC3 shRNA significantly inhibited melanoma growth, reduced xenograft melanoma weight and volume in melanoma mouse models, as compared to the group treated with Rg3 alone." (PMID 25521755, 2014). "The increased expression of HDAC3 also correlated with lymph node metastasis and clinical stage of melanoma." (PMID 25521755, 2014). "Results showed that HDAC3 was highly expressed in melanoma samples, particularly among the tumor-invaded zones, whereas non-melanoma samples showed low expression." (PMID 25521755, 2014). "We found high expression of HDAC3 in human melanoma tissues to be significantly correlated to lymph node metastasis and clinical stage of disease (p<0.05)." (PMID 25521755, 2014). "The clinicopathologic features demonstrated that a high proportion of melanoma specimens (23/32, 72.0%) stained strongly for HDAC3 (score 3–4)." (PMID 25521755, 2014). "Our data suggests that knockdown of HDAC3 (with HDAC3 siRNA) significantly inhibited A375 and C8161 melanoma cells proliferation, and the similar results were also found in MS-275 treatment cells." (PMID 25521755, 2014). "In our study, we found that HDAC3 was highly expressed in human melanoma tissues compared to that of normal control." (PMID 25521755, 2014). "Independent from vemurafenib resistance, the curcumin-harmine-isovanillin combination drug GZ17-6.02 upregulated class I MHCA and suppressed PD-L1 in PDX BRAFV600E melanoma cells, which was mediated by the downregulation of several HDACs (HDAC3, HDAC5, HDAC6, HDAC7, and HDAC8)." (PMID 39935431, 2025). "The findings that follow support the impact of ARSB and chondroitin 4-sulfation on galectin-3, c-Jun, HDAC3, and H3 on the regulation of PD-L1 expression in melanoma and suggest that ARSB may help with checkpoint inhibition." (PMID 38892038, 2024). "Hence, mast cells activation during anaphylaxis was reported to increase mouse melanoma cells dissemination in an HDAC3-dependent manner and mast cells have been shown to increase growth of Hodgkin lymphoma tumors and plasma cell tumors." (PMID 33608009, 2021).
melanoma (continued). "The relation between HDAC3/miR‐495‐3p expression and pathological characteristics of melanoma patients was analysed, and it was found that the expression of HDAC3 and miR‐495‐3p was related to TNM stage, Breslow's thickness, LNM and distant metastasis of patients." (PMID 33048450, 2020). "In addition, we demonstrated that inhibited HDAC3 enhanced miR‐495‐3p to restrict EMT in melanoma by silencing TRAF5." (PMID 33048450, 2020). "In accordance with the results, Shan et al8 have pointed out that the reduction of HDAC3 had the capacity of inhibiting proliferation of melanoma cells and arresting melanoma cells at G0/G1 phase, and it has been recently reported that HDAC3 silencing resulted in promoted killing of melanoma cells." (PMID 33048450, 2020). "HDAC3 can also decrease the angiogenic potential of melanoma cells." (PMID 30583572, 2018). "Another research implies mir-384 might play an important role in metastasis of melanoma by binding to the 3′UTR of HDAC3." (PMID 30186040, 2018). "Similar results were observed for HDAC1 and HDAC3, suggesting that some HDACs may function as melanoma suppressors." (PMID 26747087, 2016). "Another research implicated mir-384 might play an important role in metastasis of melanoma by binding to the 3'UTR of HDAC3." (PMID 27769041, 2016). "The results suggest that HDAC3 may be a potential oncogenic factor and therapeutic target in melanoma." (PMID 25521755, 2014). "By targeting HDAC3, Rg3 is a potential novel therapeutic agent for melanoma treatment." (PMID 25521755, 2014). "Correlation of HDAC3 protein expression to clinicopathologic features of melanoma Patients." (PMID 25521755, 2014). "Thus, we hypothesized that IκBζ might repress CXCL9, CXCL10, and CCL5 expression through the interaction with EZH2 and/or HDAC3 in melanoma." (PMID 40562773, 2025). "Consequently, inhibition of EZH2 or HDAC3 could re-establish chemokine expression in IκBζ-overexpressing melanoma cells, thereby validating HDAC3 and EZH2 as critical effectors downstream of IκBζ." (PMID 40562773, 2025). "Furthermore, results of cellular experiments in our study indicated that inhibited HDAC3 was able to elevate miR‐495‐3p to decelerate proliferation, migration and invasion of melanoma cells, and also induced G0/G1 phase arrest and accelerate melanoma cell apoptosis." (PMID 33048450, 2020). "Thus, FK228 can be used to down‐regulate HDAC3 to repress the development of melanoma, which could be explored in our future research." (PMID 33048450, 2020). "Thus, we inferred that HDAC3 and miR‐495‐3p played essential roles in melanoma." (PMID 33048450, 2020). "For example, inhibition of the class I HDAC1, HDAC2 and/or HDAC3 led to acetylation of the PD-L1 and PD-L2 promotors, which augmented up-regulation of PD-L1/L2 protein and RNA transcription in melanoma patients, in melanoma cell lines and in a syngeneic mouse model of melanoma." (PMID 29843754, 2018). "Thus, our results support a model in which IκBζ-mediated recruitment of EZH2 and HDAC3 represses Cxcl10, Cxcl9, and Ccl5 in melanoma, contributing to the observed lack of T-cell infiltration and immunotherapy resistance in the α-PD-1-treated, IκBζ-expressing melanoma mouse models." (PMID 40562773, 2025). "Our experiments revealed that melanoma-derived IκBζ interacts with EZH2 and HDAC3, facilitating their recruitment to the respective promoter regions, resulting in silencing of gene expression." (PMID 40562773, 2025). "For example, in squamous cell NSCLC elevated levels of histone deacetylases (HDAC), such as HDAC3 and HDAC6, are detected, that are reported to upregulate PD-L1 expression by STAT3 signalling pathway in melanoma, osteosarcoma, and pancreatic cancer." (PMID 38541208, 2024).
melanoma (continued). "In melanoma, PD-L1 seems to be directly controlled primarily by class I HDACs (HDAC1, HDAC2, HDAC3, HDAC8)." (PMID 38672128, 2024). "Culture medium from antigen-stimulated lung mast cells increased expression levels of HDAC3, MCP1, SNAIL, and Vimentin but decreased the expression of E-cadherin in B16F1 melanoma cells." (PMID 34135893, 2021). "Except for in vitro experiments, we also conducted in vivo experiment to probe into the roles of HDAC3, miR‐495‐3p and TRAF5 in melanoma cell growth." (PMID 33048450, 2020). "Our results revealed that down‐regulated HDAC3 elevates miR‐495‐3p to suppress malignant phenotypes of melanoma cells by inhibiting TRAF5, thereby repressing EMT progression of melanoma cells." (PMID 33048450, 2020). "We aim to explore the effect of histone deacetylase 3 (HDAC3) and miR‐495‐3p on epithelial‐mesenchymal transition (EMT) and oncogenicity of melanoma cells by regulating tumour necrosis factor receptor‐associated factor 5 (TRAF5)." (PMID 33048450, 2020). "Inhibited HDAC3 elevated miR‐495‐3p to suppress EMT and oncogenicity of melanoma cells by reducing TRAF5." (PMID 33048450, 2020). "Pearson correlation analysis was used to further verify the relationships between expression of HDAC3 and miR‐495‐3p/TRAF5 in the development of melanoma." (PMID 33048450, 2020). "In Malme3MR cells (anti-cancer drug-resistant melanoma cells), SIAH2 can binds to HDAC3, resulting in degradation of HDAC3 by ubiquitination." (PMID 30583572, 2018). "However, the interplay between Rg3, HDAC3, and melanoma growth remains unclear." (PMID 25521755, 2014). "Notably, inhibition of both EZH2 or HDAC3, can restore adaptive immunity in the TME and re-sensitize melanoma to immunotherapy." (PMID 40562773, 2025). "HDAC3 could bind to the promoter sequences of CAGE and inhibit the tumorigenic potential of anti-cancer drug-resistant melanoma cells." (PMID 35682560, 2022). "We aim to explore the impact of HDAC3/miR‐495‐3p/TRAF5 axis on melanoma, and we supposed that HDAC3 may mediate miR‐495‐3p to regulate the biological processes of melanoma cells by modulating TRAF5." (PMID 33048450, 2020). "HDAC3 and TRAF5 were increased while miR‐495‐3p was decreased in melanoma cells and tissues, and the low expression of miR‐495‐3p as well as high expression of HDAC3 indicated a poor prognosis of melanoma patients." (PMID 33048450, 2020). "Levels of HDAC3, miR‐495‐3p and TRAF5 in melanoma tissues and pigmented nevus tissues were determined, and the predictive roles of HDAC3 and miR‐495‐3p in prognosis of melanoma patients were measured." (PMID 33048450, 2020). "Thus, targeting IκBζ might constitute an attractive approach for sensitizing melanoma patients to immunotherapy, especially as IκBζ deletion would affect multiple oncogenic pathways, including NF-κB, STAT3, EZH2, and HDAC3." (PMID 40562773, 2025). "Consequently, the interaction of IκBζ with EZH2 and HDAC3 might be the most upstream event regulating IκBζ target genes in melanoma, whereas IκBζ-mediated gene activation derives from the additional presence of EZH2- and HDAC3-activated STAT3 and p65 at single gene promoters." (PMID 40562773, 2025). "Notably, the melanoma antigen MAGED1, which also displays hyperacetylated sites upon HDAC3 deletion/inactivation, plays a major role in apoptosis and cell cycle arrest, which could provide a further link between HDAC3 function and the reduced viability of HDAC3 CI or HDAC3 KO clones." (PMID 35994477, 2022).
colorectal cancer (29 papers, 2015 to 2025). A primary or metastatic malignant neoplasm that affects the colon or rectum. "This discovery not only enhances our mechanistic understanding of ferroptosis regulation but also unveils HDAC3 as a promising therapeutic target for ferroptosis-based intervention in colorectal cancer." (PMID 40947430, 2025). "In summary, our study identifies HDAC3 as a pivotal epigenetic regulator that suppresses ferroptosis in colorectal cancer (CRC)." (PMID 40947430, 2025). "Although current research is primarily focused on colorectal cancer, the downstream target HDAC3 has been shown to play a regulatory role in various malignancies." (PMID 40936898, 2025). "Core tip: This study reveals HDAC3 as a key epigenetic regulator that inhibits ferroptosis in colorectal cancer through modulation of the NRF2–GPX4 signaling axis." (PMID 40947430, 2025). "In this study, we identify histone deacetylase 3 (HDAC3) as a key epigenetic suppressor of ferroptosis in colorectal cancer (CRC) and delineate a novel HDAC3–NRF2–GPX4 regulatory axis that governs ferroptotic sensitivity." (PMID 40947430, 2025). "Taken together, these results suggest that TIP60 regulates apoptosis-related target genes of HDAC3 in colorectal cancer and proliferation by inhibiting HDAC3 transcription." (PMID 38805168, 2024). "In this study, we found that HDAC3 expression was increased in various cancers and that TIP60 acted as a transcriptional corepressor of HDAC3 in the colorectal cancer cell line HCT116." (PMID 38805168, 2024). "In this study, we identified a relationship between TIP60 and HDAC3 in the colorectal cancer cell line, HCT116." (PMID 38805168, 2024). "Intriguingly, HDAC3, one of the most characteristic HDACs, is dysregulated in multiple types of cancers, such as liver cancer and colorectal cancer." (PMID 36266728, 2022). "HDAC3 promotes the proliferation of colorectal cancer cells, HCC cells and glioma cells and inhibits the apoptosis of prostate cancer cells." (PMID 34880761, 2021). "This promising role of HDAC3 in regulating cancer stem cell related genes provided novel information on chemoresistance of human colorectal cancer." (PMID 32404892, 2020). "Our work revealed a novel tumor suppressor function of USP38 in human colorectal cancer via directly regulating ubiquitination status of HDAC3." (PMID 32404892, 2020). "The mechanism of histone deacetylase 3 (HDAC3) in colorectal cancer (CRC) has already been discussed." (PMID 33203425, 2020). "Since HDAC3 plays a critical role in regulation of the expression of cancer stem cell related genes, we used the selective inhibitor of HDAC3 RGFP966 to investigate the function of USP38-HDAC3 in colorectal cancer cell growth." (PMID 32404892, 2020). "Knockdown or inhibition of HDAC3 results in the downregulation of B7x in colorectal cancer cells, suggesting the potential of HDAC3 as target for regulating the tumor immune microenvironment." (PMID 32934224, 2020). "Resveratrol and piceatannol promoted PD-L1 expression via the HDAC3/p300 axis in breast and colorectal cancer cells." (PMID 31907020, 2020). "Our data provided functional insights of USP38 and HDAC3 in colorectal cancer and revealed novel mechanisms of ubiquitination mediated epigenetic regulation." (PMID 32404892, 2020). "Histone deacetylase 3 (HDAC3) is prominently over-expressed in colorectal cancer both in vitro and in vivo." (PMID 31766149, 2019). "For instance, Cbx4 represses the expression of Runx2 and metastasis of colorectal carcinoma, which is dependent on its interaction with HDAC3." (PMID 30357595, 2019). "HDAC3 can bind to the promoter sequences of Runt-related transcription factor 2 (Runx 2) and suppress the metastatic potential of colorectal cancers." (PMID 30583572, 2018). "In colorectal cancer and triple-negative breast cancer, the level of HDAC3 was upregulated." (PMID 34880761, 2021).